SF3B1 (splicing factor 3b subunit 1)
Diseases named in the same sentence as SF3B1 in open-access papers (continued):
Sharing a sentence is not in itself a finding about the gene and the disease.
cancer (continued). "Our study reveals a more complex picture in cancer, where chromosomal gains containing various splicing factors (1q gain: SF3B4, PRPF3, 2q gain: CWC22, SF3B1) and other NMD-related genes are associated with reduced NMD efficiency." (PMID 41023738, 2025). "Nonetheless, the ability to therapeutically target SF3B1 mutant cells would be clinically useful for the treatment of multiple cancer types." (PMID 40595498, 2025). "The unique pathophysiology of SF3B1 also makes it an exciting target for potential novel treatments that can inform further work for cancer therapeutics." (PMID 40124717, 2025). "Over the past few years, murine models based on the tissue-specific expression of Sf3b1-K700E have revealed that aberrant splicing events drive progression in these cancers." (PMID 40694421, 2025). "The selection of SF3B1 as a candidate target in our analysis was based upon existing literature highlighting the significance of SF3B1 alterations in various types of cancers." (PMID 38904016, 2024). "Given the important role of miRNAs in cancer and the strong effects of PlaB on miRNA production that we have observed, we advise that changes in miRNAs are taken into consideration when elucidating the anti-cancer mechanism of PlaB and other SF3B1 inhibitors." (PMID 38884273, 2024). "Currently, the predominant method of manipulating SF3B1 in tumor cells relies on small molecules, a strategy that has shown promise in various diseases, including cancer." (PMID 38975181, 2024). "and its derivatives can inhibit Splicing Factor 3B Subunit 1 (SF3B1), the most often mutated SFs across cancers and an essential spliceosome component in pre-RNA." (PMID 39000035, 2024). "For example, PB, an inhibitor of SF3B1, has been shown to exert antitumor activity in both cancer cell lines and mouse xenograft models." (PMID 39187547, 2024). "To that end, and as previously reported in other cancer types, we performed a pharmacological experimental approach by blocking the activity of SF3B1 (a central and core component of the splicing machinery) using a specific inhibitor (pladienolide-B)." (PMID 39000035, 2024). "Previous studies have focused on how mutant SF3B1 intrinsically promotes the development of cancers via aberrant RNA splicing." (PMID 39303038, 2024). "Mutations in the SF3B1 splicing factor gene can disrupt the interaction between the splicing factor and SUGP1, leading to splicing errors that can cause cancer." (PMID 38699234, 2024). "Here, we characterize the changes in alternative splicing induced by SF3B1 mutations in CLL patients and in an isogenic CLL MEC1 cell line bearing the most frequent SF3B1 cancer mutation (K700E)." (PMID 37562845, 2023). "Our target is to find out how SF3B1 has influenced the research community as a driver of some types of cancer in addition to its other roles reported in the literature." (PMID 36792691, 2023). "An orally available SF3b inhibitor, H3B-8800, preferentially inhibited tumor growth in spliceosome-mutant cancer cells, such as SF3B1 K700E, in vitro and in vivo by predominantly binding with short GC-rich regions." (PMID 37342192, 2023). "Acquisition of mutation in the splicing factor SF3B1 is a key event in the establishment and progression of MDS and other cancers." (PMID 36857430, 2023). "While the molecular function of oncogenic SF3B1 on RNA-splicing is well described, how deregulation of misspliced genes contribute to malignancy in different cancer entities is only partially understood." (PMID 37823551, 2023). "Like in other cancer types, also in PDAC the most frequently found mutation in SF3B1 led to a lysine (K) to glutamic acid (E) change at position 700 (SF3B1K700E)." (PMID 37823551, 2023). "SF3B1 plays a crucial role in various malignant tumors as a splicing factor, and there has been a long-standing exploration of small-molecule splicing modulators to SF3b as potential anti-cancer therapeutics." (PMID 38012150, 2023).
cancer (continued). "In contrast to DDX42, three SF3B1 residues (Asp894, Tyr898 and Glu902) that interact with DDX46 only are mutated in cancer." (PMID 36797247, 2023). "In our previous study, we identified five naturally occurring SUGP1 missense mutations (L515P, G519V, R625T, P636L, and R642W) flanking the G-patch in cancers that partially recapitulate mutant SF3B1 splicing dysregulation." (PMID 37977822, 2023). "Accordingly, our findings help researchers conduct more efficient and precise experiments to study the relation among mutant SF3B1, aberrant splicing, and cancer development." (PMID 36792691, 2023). "Recent mapping of cancer-associated mutations in SF3B1 suggested that these mutations disturb HEAT repeat domains, thus affecting the binding of SF3B1 with SF3B complex protein p14 and U2AF2." (PMID 36983760, 2023). "In terms of cancer-related genes, POLQ and PREX2 in the regions of gains and CASP8 and SF3B1 in the regions of loss were found in all samples, including the tissue, plasma, and peritoneal fluid." (PMID 35626111, 2022). "Pladienolide B, FD-895, GEX1A, and sudemycin E (an analog of FR901464) are inhibitors of SF3B1, and these molecules interact with SF3B1 demonstrating significant induction of cell apoptosis in cancers." (PMID 36505770, 2022). "The four MM patients with SF3B1 mutation in our cohort showed a higher percentage of cells with PRAME expression, a cancer/testis antigen that is more heavily overexpressed in MDS." (PMID 36230837, 2022). "This is different from previous observations in SF3B1-mutant cancers, which suggested a higher proportion of alternative 3′ splice site events, but were similar to a recent report in SF3B1-mutant MDS." (PMID 35039052, 2022). "SF3B1 physically interacts with SUGP1, whose genetic alterations, which are rare in cancer, mimics SF3B1-mutant splice pattern." (PMID 35885562, 2022). "Targeting splicing broadly is an active area of research with clinical trials underway in SF3B1 mutant cancers and neurological diseases." (PMID 35731869, 2022). "Taken together with the role for SF3B1 in DSB repair highlighted above, we next tested the impact of the cancer associated SF3B1K700E mutation on DSB repair." (PMID 35027467, 2022). "The most frequently mutated of these genes is SF3B1, with SF3B1K700E occurring in a wide range of cancer types at varying frequencies." (PMID 35027467, 2022). "Numerous studies have identified that mutations in SRSF1, SRSF2, SF3B1, and U2AF1, which are essential components of the major spliceosome, are associated with the development of several types of cancers." (PMID 36142830, 2022). "We previously demonstrated that modulation of splicing in cancer cells was an effective therapy in an in vivo model, both as a monotherapy with direct inhibitors of SF3B1 and in combination with other anticancer agents, with acceptable toxicity." (PMID 35582381, 2021). "The plant indole alkaloid JA stabilized SF3B1 protein in cancer cells and disrupted the interaction of SF3B1 and SF3B3 with nucleosomes." (PMID 34065983, 2021). "One of these proteins (SF3B1) is particularly relevant in the context of this review because it has been identified as a driver in many cancers." (PMID 35008179, 2021). "Of 87 patients, 21 patients were analyzed by NGS with 48 selected cancer genes including GNA11, GNAQ and FBXW7, and 66 patients were analyzed for mutations by NGS with 592 cancer genes including BAP1 and SF3B1 mutations as well as MYC amplification." (PMID 34830903, 2021). "and its derivatives can inhibit SF3B1 function and thereby exert antitumoral effects in several cancers." (PMID 34857016, 2021). "Pre-clinical studies have shown potential in the modulation of splicing in cancer cells via small molecules targeting SF3B1, namely pladienolide B (PB), spliceostatin A and herboxidiene, which interfere with the splicing modulation." (PMID 35582381, 2021).
cancer (continued). "Recent studies on cancer genomes have revealed that recurrent somatic mutations of genes encoding RNA splicing factors (e.g. SF3B1, U2AF1, SRSF2, ZRSR2) lead to altered splice site preferences, resulting in cancer-specific mis-splicing of genes." (PMID 33427197, 2021). "SF3B1, a subunit of the U2 snRNP that recognizes the BPS, is the most commonly mutated splicing regulator in numerous cancers, with a prevalence ranging from 5% in breast cancer to 81% in an MDS subtype." (PMID 33261131, 2020). "Here, we also found SF3B1 transcriptome enriched with several metabolic process, suggesting a possible role for SF3B1 in metabolic programming in cancers." (PMID 33040078, 2020). "Other factors also known to influence the same step in splicing as SF3B1, namely U2AF1 and SRSF2, are also frequently mutated in cancer." (PMID 33348896, 2020). "Cancer genome sequencing efforts have identified frequently mutated genes in UM, including GNAQ, GNA11, BAP1, SF3B1, and EIF1AX7,25." (PMID 32277165, 2020). "In this work, the impact of the splicing factor 3B subunit 1 (SF3B1) K700E mutation, a highly prevalent mutation in various cancer types, is investigated through molecular dynamics simulations." (PMID 32354150, 2020). "There are no integration sites in chromosomes 21, 22, and X. Only five genes of the many associated with MCPyV integration, namely SF3B1, TLX3, CD74, MYC, and KMT2D, are cancer-linked genes listed in the COSMIC database." (PMID 32878339, 2020). "Identification of aberrant splicing, as one of the significant cancer drivers, has brought SF3B1 into prominence due to its crucial role in recognition of the proper branch sites during splicing process." (PMID 32354150, 2020). "As HEK293T cells are sensitive to PB but are resistant to its cytotoxic effects, we reasoned that the HEK293T cell line would be well-suited for transcriptomic analyses for the discovery of SF3B1-dependent transcripts in a non-cancer-derived cell line." (PMID 33348896, 2020). "Several microbial products, including Pladienolide B and its derivative E7107, have been shown to bind and specifically inhibit the SF3B1 complex and manifest anti-cancer activities." (PMID 32350277, 2020). "While most models for SF3b1 dysfunction in cancer have focused on steps involved in BS recognition and U2 loading, it is possible that some degree of splicing dysregulation occurs through disruption of later steps." (PMID 32320410, 2020). "The prognostic and therapeutic potential of SF3B1 in other types of cancer needs to be further studied." (PMID 32905346, 2020). "We also assessed SF3B1 expression in cancer tissues compared with normal mucosa (relative SF3B1 expression) in 80 CRC patients." (PMID 30719229, 2019). "In this study, we performed a MPRA using a minigene library with degenerate sequences surrounding 3′SS to define nature of BP utilization in SF3B1-mutant cancers." (PMID 30462273, 2019). "So far, studies on SF3B1 related to cancer have focused on the malfunction of RNA splicing due to the SF3B1 mutation." (PMID 29954402, 2018). "SF3B1 is partially lost in 11% of the 10,570 cancers from the TCGA PanCan dataset (see Materials and methods for definitions of copy number states)." (PMID 28177281, 2017). "Mutations in the largest SF3b subunit, SF3B1/SF3B155, are linked to cancer and lead to alternative branch site selection." (PMID 29383138, 2017). "Previous studies using the SF3B1-targeted splicing inhibitors have shown that they are potent growth inhibitors of many different cancer cell lines." (PMID 28884683, 2017). "The extent to which SF3B1 and other splicing factors can be leveraged as therapeutic targets in cancer is not fully understood." (PMID 28177281, 2017). "Our observation that ESS1, a SF3B1K666N mutant cell line, was sensitive to partial SF3B1 suppression is consistent with a prior report that SF3B1-mutant cancer cells were found to depend on remaining wild-type copy." (PMID 28177281, 2017).
cancer (continued). "Therefore, we propose that SF3B1 mutations could be driving increased HSF1 levels in some cancers." (PMID 28445500, 2017). "To investigate the potential role of NMD, we identified differentially expressed genes between the SF3B1 mutant and wild-type samples in a joint analysis of all three cancers and performed a gene set enrichment analysis." (PMID 25768983, 2015). "Recurrent somatic missense mutations in SF3B1 are frequent in cancers, but no constitutional variant has been reported so far." (PMID 41577671, 2026). "While SF3B1, a splicing factor frequently mutated in cancers, is often targeted in therapies, these neoepitopes were present regardless of SF3B1 mutation status, suggesting an SF3B1-independent mechanism of action." (PMID 40002189, 2025). "It was observed that in two cancer cell lines harboring SF3B1 mutations, the deletion of the mutant allele did not impact cell proliferation, whereas the deletion of the wild-type allele proved lethal." (PMID 40697666, 2025). "The functions of SF3B1 and its inhibitors have been extensively evaluated in various cancers." (PMID 38671459, 2024). "This could be elucidated by the varying expression and functionality of SF3B1 and other splicing factors in normal compared to cancer cells." (PMID 38904016, 2024). "For instance, oncogenic mutations in spliceosome components SF3B1 and U2AF1 result in the aberrant use of alternative branchsites, and cryptic splice sites that often disrupt splicing of cancer‐associated transcripts." (PMID 39118304, 2024). "Nevertheless, it also implies a potential increased sensitivity to SF3B1 modulators, presenting a novel precision medicine strategy for more efficacious therapeutic interventions in addressing these exceptionally chemoresistant cancers." (PMID 38904016, 2024). "The only cancer subtypes that showed significant differences in splicing antigenicity were between SF3B1-wt and mutant samples in BRCA and HNSC, with higher splicing antigenicity in mutant samples (BRCA P value = 0.017 and Cohens d = 1.22; HNSC P value = 0.05 and Cohens d = 0.33, Wilcoxon test)." (PMID 39470352, 2024). "We found that 16 proteins interact with SF3B1 with predicted high binding affinity, eight of which have at least one direct interaction with SF3B1 HEAT repeats H4–H7, the hotspot area for cancer mutations." (PMID 37977822, 2023). "In addition, seven SF3B1 residues that interact with both DDX46 and DDX42 are targeted for mutations in cancer, including the most frequently mutated residue Lys700." (PMID 36797247, 2023). "Finally, we demonstrated that depletion of hsa_circ_0000228, the most upregulated ZEB1‐circRNA in SF3B1‐mutated MDS, affects mitochondrial functions and interacts with cancer‐related miR‐1248." (PMID 37408496, 2023). "Pan-cancer analyses of >10,000 samples in TCGA also revealed a number of SUGP1 cancer-associated mutations flanking the SUGP1 G-patch motif (G-patch) that partially recapitulate mutant SF3B1 missplicing, suggesting a mechanistic link between SF3B1 and SUGP1." (PMID 37977822, 2023). "Pladienolide B is an SF3B1 inhibitor widely used in cancer research." (PMID 38012150, 2023). "Given the preferential dependence on splicing function in MDS-associated cells with RNA splicing factor mutations and the progressively more prominent pathogenic role of SF3B1 spliceosomal mutations in MDS and cancer, interest in the pharmacology of targeted splicing has been stimulated." (PMID 37007111, 2023). "Several SF3B1 hotspot mutations have been described at the C-terminal of the HEAT (Huntingtin, Elongation factor 3, protein phosphatase 2A, Targets of rapamycin 1) repeats with a different prevalence according to the cancer type." (PMID 35565242, 2022).
cancer (continued). "Additionally, the Genomics of Drug Sensitivity in Cancer (GDSC) dataset was explored to analyze the potential implication of SF3B1 in pharmacological resistance." (PMID 35086552, 2022). "Thus, our study sheds light on a new aspect of the oncogenic impact of mutant SF3B1 and provides an appealing therapeutic approach based on glycolysis inhibition, possibly combined with targeting other cancer-related pathways." (PMID 35565242, 2022). "Furthermore, a tumorsphere formation assay (used to quantify the proliferation capacity of cancer stem-like progenitor cells) revealed that SF3B1 blockade drastically decreased the number and area of tumorspheres in both cell lines." (PMID 35086552, 2022). "The core splicing factor SF3B1 is heavily altered in cancer and can be inhibited by Pladienolide-B, but its actionability in PDAC is unknown." (PMID 34857016, 2021). "Most of the SF3B1 mutations are located in its HEAT repeats, especially in HEATs 4–12, where five residues, R625, H662, K666, K700 and E902, are hotspots and most of them exhibit cancer lineage specificities." (PMID 34723968, 2021). "Commonly, the core components of spliceosomes, U2AF1 and SF3B1, are altered in cancer." (PMID 34356101, 2021). "This way, they could induce individual depletion of wild type and mutant SF3B1 proteins in cancer cell lines." (PMID 34065983, 2021). "While selective lethality on cancer cells and anticancer activity of these compounds were shown, whether SF3B1 is a truly cancer-selective target is somewhat controversial." (PMID 34065983, 2021). "Furthermore, targeting SF3B1 function with Pladienolide-B reduces multiple cancer features in PDAC cells (proliferation, migration, and colony and sphere formation) by altering relevant signaling pathways and splicing events." (PMID 34857016, 2021). "SRSF1, along with SF3B1, are also involved in apoptosis modulation in cancer through AS." (PMID 34356101, 2021). "The Splicing Factor 3B Subunit 1 (SF3B1) is a spliceosome component essential in pre-RNA processing and the most frequently mutated splicing factor across cancers, particularly in hematological malignancies but also in solid tumors, including PDAC (although at a much lower frequency, 4% of cases)." (PMID 34857016, 2021). "Interestingly, some of these genes (U2AF1, SF3B1, RBM10) are core players of alternative splicing, a key cellular process whose alteration is emerging as a widespread hallmark in every cancer studied and, most importantly, an attractive therapeutic target." (PMID 34857016, 2021). "Therefore, studies of these mutants have revealed important information about the role of SF3B1 in cancer but cannot reveal the role of SF3B1 in normal cellular physiology." (PMID 33348896, 2020). "We thus identified an AS event that discriminates between the effects of targeting Sm genes versus SF3B1 and that may contribute to the observed cancer-selective lethal phenotype of silencing Sm genes." (PMID 32545483, 2020). "Furthermore, by identifying substrates in a non-cancer-derived background, we can begin to understand the baseline role that SF3B1 plays in the cell." (PMID 33348896, 2020). "Interestingly, NPH2L1 and SF3B1 are splice factors and both cancer and precancerous cells displayed an increased dependency on splicing." (PMID 32047167, 2020). "In addition, aberrant mutations of SF3B1 in a gain-of-function form and high expression of SRSF3 are commonly associated with some types of cancers." (PMID 33086735, 2020).